DCLRE1B (DNA cross-link repair 1B)
Description:
5'-3' exonuclease that plays a central role in telomere maintenance and protection during S-phase. Participates in the protection of telomeres against non-homologous end-joining (NHEJ)- mediated repair, thereby ensuring that telomeres do not fuse. Plays a key role in telomeric loop (T loop) formation by being recruited by TERF2 at the leading end telomeres and by processing leading-end telomeres immediately after their replication via its exonuclease activity: generates 3' single-stranded overhang at the leading end telomeres avoiding blunt leading-end telomeres that are vulnerable to end-joining reactions and expose the telomere end in a manner that activates the DNA repair pathways. Together with TERF2, required to protect telomeres from replicative damage during replication by controlling the amount of DNA topoisomerase (TOP1, TOP2A and TOP2B) needed for telomere replication during fork passage and prevent aberrant telomere topology. Also involved in response to DNA damage: plays a role in response to DNA interstrand cross-links (ICLs) by facilitating double-strand break formation. In case of spindle stress, involved in prophase checkpoint. Possesses beta-lactamase activity, catalyzing the hydrolysis of penicillin G and nitrocefin. Exhibits no activity towards other beta-lactam antibiotic classes including cephalosporins (cefotaxime) and carbapenems (imipenem).
Synonyms: SNMIB; SNM1B; FLJ12810; FLJ13998; APOLLO; DKCB8
Tractability: Small molecule: a structure with a bound ligand is known. PROTAC: UniProt records ubiquitination sites on it; ubiquitination databases record sites on it.
Target class: Enzyme; Hydrolase
Gene: Protein-coding gene on chromosome 1 (113,904,403 to 113,914,086, forward strand). Ensembl gene ENSG00000118655.
Subcellular location: Chromosome, telomere; Nucleus; Cytoplasm, cytoskeleton, microtubule organizing center, centrosome
Subcellular location (Human Protein Atlas): Nuclear bodies; Nucleoplasm
Pathways (Reactome):
DNA Repair: Fanconi Anemia Pathway
Gene Ontology:
Molecular function: 5'-3' exonuclease activity; beta-lactamase activity; protein binding; protein homodimerization activity; protein-containing complex binding; 5'-3' DNA exonuclease activity; damaged DNA binding
Biological process: interstrand cross-link repair; protection from non-homologous end joining at telomere; telomere capping; telomere maintenance; telomere maintenance via telomere lengthening; double-strand break repair via nonhomologous end joining; telomeric 3' overhang formation; telomeric loop formation
Cellular component: centrosome; chromosome, telomeric region; nuclear body; nucleoplasm; nucleus
Genetic constraint (gnomAD): Loss-of-function variants: 6 observed, 21.75 expected, observed/expected ratio (o/e) 0.28, 90% interval 0.15 to 0.55. The upper end of that interval is the gene's LOEUF score, 0.55, which puts it in group 2 of 6, group 1 being the genes least tolerant of losing a copy. Missense variants: 622 observed, 691.28 expected, observed/expected ratio (o/e) 0.9, 90% interval 0.84 to 0.96. Synonymous variants: 258 observed, 272.05 expected, observed/expected ratio (o/e) 0.95, 90% interval 0.86 to 1.05.
Homologues: Orthologues: chimpanzee DCLRE1B (99% identical), macaque DCLRE1B (95% identical), rabbit DCLRE1B (83% identical), dog DCLRE1B (81% identical), pig DCLRE1B (81% identical), rat Dclre1b (79% identical), mouse Dclre1b (78% identical), tropical clawed frog dclre1b (44% identical), zebrafish dclre1b (42% identical), Caenorhabditis elegans mrt-1 (20% identical), Caenorhabditis elegans pot-2 (2% identical), Caenorhabditis elegans pot-3 (2% identical). Paralogues in human: DCLRE1C (23% identical), DCLRE1A (21% identical).
Diseases named in the same sentence as DCLRE1B in open-access papers:
DCLRE1B is named in the same sentence as 27 diseases in open-access papers, as found by Europe PMC text mining. Sharing a sentence is not in itself a finding about the gene and the disease. The quoted sentences say what the papers report.
breast carcinoma (4 papers, 2016 to 2025). "DCLRE1B rs3761936 is strongly associated with breast cancer and cervical cancer risk in Bangladeshi women." (PMID 40920780, 2025). "Except for the mentioned limitations, our present case-control study confirmed that DCLRE1B rs3761936 polymorphism has a strong association with breast cancer and cervical cancer risk in Bangladeshi women." (PMID 40920780, 2025). "Although the evidence was somehow confusing and contradictory, we aimed to evaluate the risk association of DCLRE1B rs3761936 polymorphism in Bangladeshi breast cancer and cervical cancer patients." (PMID 40920780, 2025). "In the case of rs3761936 of DCLRE1B gene, this missense mutation upregulates the mRNA expression in breast cancer and cervical cancer patients." (PMID 40920780, 2025). "DCLRE1B rs3761936 polymorphism is strongly associated with a significantly increased risk of breast cancer and cervical cancer in Bangladeshi women." (PMID 40920780, 2025). "We used six genetic models to quantify the risk of DCLRE1B rs3761936 polymorphism on breast cancer patients." (PMID 40920780, 2025). "Our Kaplan–Meier analysis showed that the higher expression of the DCLRE1B gene was associated with poorer relapse-free survival for breast cancer patients." (PMID 34889888, 2021). "Noticeable differences between the genotypic frequencies of the patients and controls indicate that DCLRE1B rs3761936 polymorphism might be associated with an increased risk of breast cancer." (PMID 40920780, 2025). "Based on the prior studies, we chose the rare genetic variant of the DCLRE1B gene, a bi-allelic polymorphism rs3761936, that may influence breast cancer and cervical cancer development." (PMID 40920780, 2025). "Quantitative risk analysis of DCLRE1B rs3761936 polymorphism on breast cancer patients." (PMID 40920780, 2025). "Therefore, the aim of our present study is to evaluate the risk association of breast cancer and cervical cancer development with DCLRE1B rs3761936 polymorphism in Bangladeshi women." (PMID 40920780, 2025). "Overexpression of rs3761936 of DCLRE1B gene has been observed in both breast cancer and cervical cancer patients." (PMID 40920780, 2025). "The rs11552449, a missense variant in the first exon of gene DCLRE1B (HGNC:17641) in the 1p13.2 loci, has been reported for association with breast cancer risk." (PMID 34889888, 2021). "The DNA cross-link repair 1B (DCLRE1B) gene is involved in repair of inter-strand cross-links and a common allele of this gene (rs11552449) is associated with increased risk of breast cancer." (PMID 27392074, 2016). "Although the rs3761936 polymorphism of DCLRE1B gene might have a high susceptibility to developing breast cancer and cervical cancer, no specific case-control studies were conducted to evaluate the association." (PMID 40920780, 2025).
pancreatic cancer (4 papers, 2019 to 2025). "DNA cross‐link repair 1B (DCLRE1B), a 5′‐to‐3′ exonuclease, a DNA repair gene, is upregulated in pancreatic cancer, promotes the proliferation of pancreatic cancer cells, and is associated with poor prognosis." (PMID 40448344, 2025). "Additionally, the upregulated Expression of DCLRE1B in the liver, kidney, and pancreatic cancers is associated with poor prognosis." (PMID 39445019, 2024). "In vitro experiments demonstrated that DCLRE1B facilitates the proliferation and migration of pancreatic cancer cells." (PMID 39445019, 2024). "DCLRE1B mRNA expression in pancreatic cancer cells and tissues was considerably greater compared to that in healthy pancreatic epithelial cells and tissues." (PMID 37936074, 2023). "Immunohistochemistry assay also confirmed the up-regulated expression of DCLRE1B protein in pancreatic cancer tissues." (PMID 37936074, 2023). "In our research, we explored the expression, prognosis, and immune infiltration of DCLRE1B in pan-cancer, including pancreatic cancer." (PMID 37936074, 2023). "The DCLRE1B’s biological roles in pancreatic cancer cells were ascertained by employing wound healing, in vitro CCK-8, and MeRIP-qPCR assays." (PMID 37936074, 2023). "In addition, high expression of DCLRE1B gene in renal, liver and pancreatic cancers resulted in poor prognosis." (PMID 37936074, 2023). "In addition, the DCLRE1B protein’s high expression in pancreatic cancer was further confirmed as per western blotting and immunohistochemistry." (PMID 37936074, 2023). "Pathologically, DCLRE1B gene alterations are unfavorable for renal, liver, and pancreatic cancer." (PMID 31108893, 2019). "Therefore, we considered that DCLRE1B may affect the advancement of pancreatic cancer by mediating the STAT3/PD-L1 signaling pathway." (PMID 37936074, 2023).
dyskeratosis congenita (2 papers, 2017 to 2023). Dyskeratosis congenita (DC) is a rare ectodermal dysplasia that often presents with the classic triad of nail dysplasia, skin pigmentary changes, and oral leukoplakia associated with a high risk of bone marrow failure (BMF) and cancer.
glioma (2 papers, 2013 to 2025). A benign or malignant brain and spinal cord tumor that arises from glial cells (astrocytes, oligodendrocytes, ependymal cells). "Rs12022378 in the DCLRE1B gene was also found by recessive model associated with glioma risk (OR, 1.42; 95% CI, 1.05-1.93; P = 0.0246)." (PMID 23683922, 2013). "Four tSNPs were detected to be associated with glioma by model association analyses including rs6010620 and rs2297440 in the RTEL1 gene, rs12022378 in the DCLRE1B gene, and rs12917 in the MGMT gene." (PMID 23683922, 2013).
immune deficiency (2 papers, 2017 to 2024). "DCLRE1B was reportedly implicated in an inherited bone marrow failure syndrome associated with immune deficiency." (PMID 38336809, 2024).
ovarian carcinoma (2 papers, 2019 to 2024). A malignant neoplasm originating from the surface ovarian epithelium. "Taken together, OD extract effectively promoted cell death in cisplatin-resistant ovarian cancer cells under cisplatin treatment through modulating KDM1B and DCLRE1B." (PMID 31108893, 2019). "Three of the four human ovarian cancer patient data sets, including (a) Tumor Ovarian-Anglesio, (c) Tumor Ovarian-Bowtell and (d) Tumor Ovarian-Expo data sets, showed this KDM1B and DCLRE1B correlation with R square < 1 and p-value < 0.05." (PMID 31108893, 2019).
autoimmune disorders (1 paper, 2020). "In PhenoScanner49, TAP2, DCLRE1B, and SKIV2L have been previously mapped in GWAS to autoimmune disorders such as rheumatoid arthritis (RA)." (PMID 32358504, 2020).
breast invasive cancer (1 paper, 2025). "Only a few genetic databases showed that protein expression with the polymorphic allele of DCLRE1B gene was over-expressed in both breast invasive cancer cells and cervical carcinoma cells." (PMID 40920780, 2025).
cervical cancer (1 paper, 2025). A primary or metastatic malignant neoplasm involving the cervix. "Although this is the first case-control study of DCLRE1B rs3761936 polymorphism with the risk of breast and cervical cancer, there were some limitations that should be mentioned." (PMID 40920780, 2025). "The UALCAN database also revealed the presence of significantly high expression of DCLRE1B mRNA in cervical cancer tissues compared to healthy tissues, which indicates a vital role of the DCLRE1B gene in the development of cervical cancer." (PMID 40920780, 2025).
mesothelioma (1 paper, 2023). A usually malignant and aggressive neoplasm of the mesothelium which is often associated with exposure to asbestos. "The maximum gene alteration rate of DCLRE1B was recorded for pan-cancer patients with uterine corpus endometrial carcinoma, skin cutaneous melanoma, mesothelioma and pheochromocytoma and paraganglioma with deep deletion (> 3%) as the primary type." (PMID 37936074, 2023).
cancer (11 papers, 2016 to 2025). A tumor composed of atypical neoplastic, often pleomorphic cells that invade other tissues. "Data regarding involvement of POT1 and DCLRE1B genes in telomeropathies are only recently emerging with proposals that these genes should be included on cancer‐risk predisposing multigene panel tests as well as genetic tests for telomere biology dysfunction." (PMID 37994393, 2024). "With the exception of KICH, UCEC, OV, GBM, and KIRC, DCLRE1B methylation was exhibited to be substantially linked to DCLRE1B mRNA expression in the majority of cancers." (PMID 37936074, 2023). "DCLRE1B has been reported to cause poor prognosis in a variety of cancers." (PMID 37936074, 2023). "Similarly, expression of DCLRE1B exhibited substantial association with immune cells in several cancer types." (PMID 37936074, 2023). "According to the findings, DCLRE1B was significantly associated with cancer immunity and prognosis." (PMID 37936074, 2023). "The upregulated Expression of DCLRE1B in human cancers promotes cancer initiation and progression by modulating processes, such as immune cell infiltration." (PMID 39445019, 2024). "In human cancer, the overexpression of DCLRE1B was generally observed, which aided cancer onset and advancement via a variety of processes comprising control of the immune cells’ tumor infiltration." (PMID 37936074, 2023). "The findings revealed that DCLRE1B was substantially overexpressed in the majority of cancer types including PAAD, which was verified at the protein and mRNA levels using PCR, WB, and IHC analysis." (PMID 37936074, 2023). "The findings above exhibited a strong link between DCLRE1B expression and prognosis in several cancer types." (PMID 37936074, 2023). "According to this study’s findings, in a few malignant tumors, DCLRE1B is a candidate immunotherapeutic and prognostic biomarker." (PMID 37936074, 2023). "We discovered that, in GEPIA, the elevated DCLRE1B expression level was linked to the more unfavorable OS and DFS across cancers." (PMID 37936074, 2023). "To illustrate the potential function of DCLRE1B in cancer, we conducted KEGG and Reactome pathway analysis using PAAD as an example." (PMID 37936074, 2023). "In conclusion, we first explored the differential expression and prognostic value of DCLRE1B in pan-cancer." (PMID 37936074, 2023). "It was discovered that DCLRE1B expression had a positive link to ICP genes in many types of cancer, especially in PAAD, in which the correlation coefficients of DCLRE1B with PD-1, PD-L1, PD-L2, and CTLA4 were 0.358, 0.577, 0.593 and 0.378, respectively." (PMID 37936074, 2023). "In human cancers, several databases were employed for evaluating the prognostic value of DCLRE1B expression." (PMID 37936074, 2023). "Subsequently, utilizing the TISIDB website, the correlations of DCLRE1B mRNA expression with tumor stage and grade among human cancers were ascertained." (PMID 37936074, 2023). "Moreover, according to the outcomes, the majority of cancer types had considerably greater DCLRE1B mRNA expression levels, which agreed with the findings derived based on the TIMER database." (PMID 37936074, 2023). "Expression of DCLRE1B was found to be substantially related to the cancer patients’ prognoses." (PMID 37936074, 2023). "Thus, ascertaining the processes via which DCLRE1B modulates tumorigenesis was the goal of the extensive bioinformatics investigation of pan-cancer datasets in the present research." (PMID 37936074, 2023). "The finding revealed that 1.6% of cancer patients had DCLRE1B genetic abnormalities." (PMID 37936074, 2023). "According to the pan-cancer analysis, in numerous solid tumors, DCLRE1B upregulation was observed." (PMID 37936074, 2023). "Investigations on the pan-cancer DCLRE1B methylation landscape also took place." (PMID 37936074, 2023). "We could find that DCLRE1B expression showed a significant correlation with immune cells across multiple cancer types." (PMID 37936074, 2023).
cancer (continued). "It was discovered that DCLRE1B expression was positively associated with ICP genes in many types of cancer, especially in PAAD, in which the correlation coefficients of DCLRE1B with PD-1, PD-L1, PD-L2, and CTLA4 were 0.358, 0.577, 0.593 and 0.378, respectively." (PMID 37936074, 2023). "Thus it can be seen that high DCLRE1B expression might predict good immunotherapy therapeutic efficacy, and DCLRE1B may serve as an ideal immunotherapeutic target in pan-cancer." (PMID 37936074, 2023). "Nonetheless, there is no research on DCLRE1B’s biological role in pan-cancer datasets." (PMID 37936074, 2023).
tumor (6 papers, 2015 to 2024). "In contrast, DCLRE1B expression was inversely linked to tumor stage in BRAC, CHOL, COAD, STAD, and TGCT." (PMID 37936074, 2023). "Correspondingly, higher DCLRE1B mRNA expression was linked to higher tumor grade in HNSC, KIRC, LGG, LIHC, and UCEC." (PMID 37936074, 2023). "Recent studies have confirmed the role of DCLRE1B in immune regulation and tumor immunotherapy response." (PMID 39445019, 2024). "The link between DCLRE1B expression and tumor-infiltrating immune cell (TIIC) levels in various tumors was then investigated employing the Sangerbox database." (PMID 37936074, 2023). "Nonetheless, whether DCLRE1B contributes to the oncogenesis of particular tumor types is still unknown." (PMID 37936074, 2023). "Furthermore, we confirmed that DCLRE1B may play a role in tumor immune response regulation, which is expected to be a target of tumor immunotherapy." (PMID 37936074, 2023). "Of them, ARHGEF16 and DCLRE1B were excluded due to their unknown correlation with the tumor." (PMID 25475780, 2015).
DCLRE1B also shares sentences with these, for which no sentence is quoted: prostate carcinoma (2 papers); bone marrow failure (1); bone marrow failure syndrome (1); colorectal cancer (1); Fanconi anemia (1); immunodeficiency (1); liver cancer (1); lung carcinoma (1); Nijmegen breakage syndrome (1); paraganglioma (1); pheochromocytoma (1); rheumatoid arthritis (1); short telomere syndrome (1); skin cutaneous melanoma (1); uterine corpus endometrial carcinoma (1).